PLA2G12A (phospholipase A2 group XIIA)
Description:
PA2 catalyzes the calcium-dependent hydrolysis of the 2-acyl groups in 3-sn-phosphoglycerides. Does not exhibit detectable activity toward sn-2-arachidonoyl- or linoleoyl-phosphatidylcholine or -phosphatidylethanolamine.
Synonyms: PLA2G12; GXII; ROSSY
Tractability: Small molecule: a high-quality ligand is known. Antibody: UniProt places it where antibodies can reach, with high confidence; its Gene Ontology location is reachable by antibodies, with high confidence; UniProt predicts a signal peptide or a membrane-spanning region. PROTAC: its protein half-life has been measured; a small molecule that binds it is known.
Target class: Enzyme; Hydrolase
Gene: Protein-coding gene on chromosome 4 (109,709,989 to 109,730,070, reverse strand). Ensembl gene ENSG00000123739.
Subcellular location: Secreted; Cytoplasm
Pathways (Reactome):
Metabolism: Acyl chain remodelling of PC; Acyl chain remodelling of PE; Acyl chain remodelling of PG; Acyl chain remodelling of PI; Acyl chain remodelling of PS; Synthesis of PA
Gene Ontology:
Molecular function: protein binding; phospholipase A2 activity; calcium ion binding
Biological process: arachidonate secretion; lipid catabolic process; phospholipid metabolic process
Cellular component: extracellular region; cytoplasm
Genetic constraint (gnomAD): Loss-of-function variants: 9 observed, 11.94 expected, observed/expected ratio (o/e) 0.75, 90% interval 0.45 to 1.31. The upper end of that interval is the gene's LOEUF score, 1.31, which puts it in group 5 of 6, group 1 being the genes least tolerant of losing a copy. Missense variants: 150 observed, 166.08 expected, observed/expected ratio (o/e) 0.9, 90% interval 0.79 to 1.03. Synonymous variants: 56 observed, 67.45 expected, observed/expected ratio (o/e) 0.83, 90% interval 0.67 to 1.04.
Homologues: Orthologues: chimpanzee PLA2G12A (100% identical), dog PLA2G12A (94% identical), pig PLA2G12A (93% identical), mouse Pla2g12a (89% identical), rat Pla2g12a (87% identical), guinea pig PLA2G12A (85% identical), tropical clawed frog pla2g12a (61% identical), zebrafish pla2g12a (59% identical), Drosophila melanogaster GXIVsPLA2 (26% identical), Caenorhabditis elegans C31H1.5 (21% identical), Caenorhabditis elegans F44B9.10 (13% identical). Paralogues in human: PLA2G12B (42% identical).
Diseases named in the same sentence as PLA2G12A in open-access papers:
PLA2G12A is named in the same sentence as 21 diseases in open-access papers, as found by Europe PMC text mining. Sharing a sentence is not in itself a finding about the gene and the disease. The quoted sentences say what the papers report.
schizophrenia (4 papers, 2016 to 2024). A major psychotic disorder characterized by abnormalities in the perception or expression of reality. "Increases in Ban I polymorphism of the cPLA2 gene and PLA2G12A polymorphism of the sPLA2 gene have been shown in schizophrenia of different ethnic groups." (PMID 32620164, 2020). "To extend our previous findings, we further investigated the genetic association between PLA2G12A polymorphisms and schizophrenia, and significant results were obtained." (PMID 27434078, 2016). "In the present study, we conducted a case-control study to examine the effect of four PLA2G12A SNPs on schizophrenia risk in a Han Chinese population." (PMID 27434078, 2016). "Genotype distribution and allele frequency differences between schizophrenia patients and healthy controls for four PLA2G12A SNPs." (PMID 27434078, 2016). "Sex-specific genotype distribution and allele frequency differences between schizophrenia patients and healthy controls for four PLA2G12A SNPs." (PMID 27434078, 2016). "The Chi-square (χ2) test and haplotype analysis were performed to analyze the association of PLA2G12A SNPs and schizophrenia using the software packages SPSS 16.0 and Haploview 4.2." (PMID 27434078, 2016). "The association between PLA2G12A haplotypes and schizophrenia." (PMID 27434078, 2016). "SNP rs3087494 in the 3’ UTR of PLA2G12A was significantly associated with schizophrenia." (PMID 27434078, 2016). "Our study demonstrated that PLA2G12A SNPs or haplotypes might influence the susceptibility to schizophrenia in the Han Chinese population from Northeast China." (PMID 27434078, 2016). "The purpose of this study was to explore the association between single nucleotide polymorphisms (SNPs) in the phospholipase A2 (PLA2), group XIIA gene (PLA2G12A) and schizophrenia." (PMID 27434078, 2016).
atherosclerosis (3 papers, 2020 to 2023). A disease characterized by the build-up of fatty material and calcium deposition in the arterial wall resulting in partial or complete occlusion of the arterial lumen. "The pla2g12a (Phospholipase A2 Group 12A) gene is up-regulated in inflammation and atherosclerosis." (PMID 32033529, 2020).
pulmonary arterial hypertension (2 papers, 2014 to 2023). Pulmonary arterial hypertension (PAH) is a group of diseases characterized by mean pulmonary artery pressure >20 mmHg and elevated pulmonary arterial resistance leading to right heart failure. "Many genes are functionally related to high-altitude physiology, such as angiogenesis (RGCC), pulmonary hypertension remodeling (PLA2G12A), oxygen intake (C9ORF3), neural response (GRID1 and GRIN2B), melanin synthesis (MITF, PDGFRB and PIK3R3) and heart development (FOXS1, GAA and MYLK2)." (PMID 25270331, 2014). "A genome RNA expression profiling study had shown upregulation of PLA2G12A in addition to PLA2G1B and PLA2G2D in patients with pulmonary arterial hypertension secondary to IPF." (PMID 37048117, 2023). "These genes, such as PLA2G12A, RGCC, C9ORF3, GRIN2B, GRID1 and EPAS1, are involved in high-altitude physiology including angiogenesis, pulmonary hypertension, oxygen intake, defense response and erythropoiesis." (PMID 25270331, 2014).
colon cancer (1 paper, 2023). "Finally, the candidate functionality was validated in vitro using three different colon cancer cell lines, revealing that PLA2G12A deficiency increases cell proliferation, migration, and invasion." (PMID 37446068, 2023).
diabetes (1 paper, 2016). "For example, in subjects with prediabetes versus controls, cytochrome P450, family 4, subfamily F, polypeptide 3 (CYP4F3), CYP4F8, Phospholipase A2, group IIC (PLA2G2C), and PLA2G4E were differentially methylated, while in subjects with diabetes versus prediabetes, CYP2E1 and PLA2G12A were involved." (PMID 27555869, 2016).
hypoplastic left heart syndrome (1 paper, 2012). Hypoplastic left heart syndrome (HLHS) refers to the abnormal development of the left-sided cardiac structures, resulting in obstruction to blood flow from the left ventricular outflow tract. "Comparing our results with loci suggested by previous studies, we find that only the locus on 10q22 containing PLA2G12A overlaps with a locus identified in a linkage scan for hypoplastic left heart syndrome." (PMID 22969434, 2012).
Insulin resistance (1 paper, 2024). Increased resistance towards insulin, that is, diminished effectiveness of insulin in reducing blood glucose levels. "Through examination of rare protein-coding variation from exome sequencing, we find that loss-of-function in PLA2G12A increases insulin resistance as measured by TG/HDL." (PMID 39277575, 2024). "We highlight two phospholipase encoding genes, PLA2G12A and PLA2G6, which liberate arachidonic acid and improve insulin sensitivity, and VGLL3, a transcriptional co-factor that increases insulin resistance partially through enhanced adiposity." (PMID 39277575, 2024).
lung fibrosis (1 paper, 2023). "Interestingly, all these six dominant isoforms were found to be present only in structural cells like fibroblasts (PLA2G2A and PLA2G5), mesothelial cells (PLA2G2A) and epithelial cells (PLA2G1B, PLA2G3, PLA2G10 and PLA2G12A) that are key players in lung fibrosis." (PMID 37048117, 2023).
steatosis (1 paper, 2024). Increased lipid within the cytoplasm of cells. "Genes involved in steatosis (Cd36, Lpl), hepatoxicity (Avpr1a, Pla2g12a), necrosis (Serpine1), fatty acid metabolism (Acox1, Cpt1b, Cyp4a10, Ehhadh), lipid transport (Apoa1), and PPAR transcription factors (Pparδ) were altered with PFHpS exposure compared to vehicle-exposed animals." (PMID 39066581, 2024).
tumor (8 papers, 2008 to 2023). "We propose PLA2G12A as a prognostic biomarker in early-stage CRC, providing evidence that its deficiency promotes tumor growth and dissemination, unveiling novel functions for this poorly characterized phospholipase." (PMID 37446068, 2023). "To further investigate the potential of PLA2G12A as a clinical prognostic marker, we assessed its role in tumor growth and development." (PMID 37446068, 2023). "Overall, our study identifies PLA2G12A as a prognostic biomarker of early-stage CRC, providing evidence that its deficiency promotes tumor growth and dissemination." (PMID 37446068, 2023). "In fact, the in vitro data generated in this study indicate that the downregulation of PLA2G12A increases malignant behavior in intestinal cells, altering tumor cell growth, migration, and invasion." (PMID 37446068, 2023). "We found one gene, PLA2G12A, whose low expression was correlated with tumor recurrence and a poor clinical outcome." (PMID 37446068, 2023). "The TAM‐selective expression of autotaxin and PLA2G7 and the cell type‐independent high expression of PLA2G12A were confirmed analyzing the secretome of patient‐derived tumor cells, TAMs, and TATs in short‐term cultures (conditioned medium) by LC‐MS/MS‐based proteomics." (PMID 30353652, 2019). "Importantly, the protein levels of 3 phospolipases (PLA2G2, PLA2G7, and PLA2G12A) measured in ascites fluid are consistent with mRNA expression levels in tumor cells and TAMs." (PMID 27215396, 2016). "PLA2G12A has been reported to be highly expressed in normal and tumor tissues from the colon, which suggests that reduced expression, as reported in this study, might contribute to an oncogenic transformation in a subset of early onset CRCs." (PMID 20459617, 2010). "In this study, we performed wide molecular screening of genes potentially involved in tumor progression in an in vivo Drosophila CRC model and a subsequent validation of its prognostic power in two independent human cohorts, and discovered a novel putative tumor suppressor gene for CRC, PLA2G12A." (PMID 37446068, 2023). "Phospholipases, such as PLA2G16, PLA2G12A and PLA2G4A were not highly expressed in the tumour tissues." (PMID 28886030, 2017). "No variation in expression between the tumours and normal mucosa was observed for PLA2G1B, PLA2G2A, PLA2G2F, PLA2G10, PLA2G12A and PLA2G12B and for the M-type sPLA2 receptor (PLA2R1)." (PMID 18212756, 2008).
cancer (3 papers, 2023 to 2025). A tumor composed of atypical neoplastic, often pleomorphic cells that invade other tissues. "PLA2G12A codify for a member of the family of secreted phospholipases A2 (PLA2s), enzymes that hydrolyze phospholipids and are involved in several processes related to inflammation and cancer." (PMID 37446068, 2023).
PLA2G12A also shares sentences with these, for which no sentence is quoted: asthma (2 papers); infection (2); acute myocardial infarction (1); airway hyperresponsiveness (1); cholestasis (1); colorectal cancer (1); liposarcoma (1); phospholipidosis (1); prediabetes (1); pulmonary hypertension (1).